SLURP2 (secreted LY6/PLAUR domain containing 2)
Description:
Binds and may modulate the functional properties of nicotinic and muscarinic acetylcholine receptors. May regulate keratinocytes proliferation, differentiation and apoptosis. In vitro moderately inhibits ACh-evoked currents of alpha-3:beta-2-containing nAChRs and strongly these of alpha-4:beta-2-containing nAChRs, modulates alpha-7-containing nAChRs, and inhibits nicotine-induced signaling probably implicating alpha-3:beta-4-containing nAChRs. Proposed to act on alpha-3:beta-2 and alpha-7 nAChRs in an orthosteric, and on mAChRs, such as CHRM1 and CHRM3, in an allosteric manner.
Synonyms: SLURP-2
Tractability: Antibody: UniProt places it where antibodies can reach, with high confidence; UniProt predicts a signal peptide or a membrane-spanning region; its Gene Ontology location is reachable by antibodies, with medium confidence.
Gene: Protein-coding gene on chromosome 8 (142,764,338 to 142,769,828, reverse strand). Ensembl gene ENSG00000283992.
Subcellular location: Secreted
Gene Ontology:
Molecular function: acetylcholine receptor binding; acetylcholine receptor regulator activity; acetylcholine receptor inhibitor activity
Biological process: acetylcholine receptor signaling pathway; regulation of neurotransmitter receptor activity
Cellular component: extracellular region; plasma membrane; synapse
Genetic constraint (gnomAD): Loss-of-function variants: 4 observed, 8.31 expected, observed/expected ratio (o/e) 0.48, 90% interval 0.24 to 1.1. That is too few expected variants to judge how well the gene tolerates losing a copy. Missense variants: 118 observed, 126.12 expected, observed/expected ratio (o/e) 0.94, 90% interval 0.81 to 1.09. Synonymous variants: 58 observed, 56.71 expected, observed/expected ratio (o/e) 1.02, 90% interval 0.83 to 1.27.
Homologues: Orthologues: chimpanzee SLURP2 (100% identical), guinea pig SLURP2 (63% identical).
Diseases named in the same sentence as SLURP2 in open-access papers:
SLURP2 is named in the same sentence as 6 diseases in open-access papers, as found by Europe PMC text mining. Sharing a sentence is not in itself a finding about the gene and the disease. The quoted sentences say what the papers report.
cancer (1 paper, 2022). A tumor composed of atypical neoplastic, often pleomorphic cells that invade other tissues. "Differential gene analysis revealed 319 genes upregulated in tumor-derived fibroblasts, such as DCN and SFRP4, and 214 genes upregulated in cancer cells, such as SPRR1B and SLURP2." (PMID 36357663, 2022).
SLURP2 also shares sentences with these, for which no sentence is quoted: colorectal adenocarcinoma (1 paper); esophageal cancer (1); mal de Meleda (1); psoriasis (1); tumor (1).